ZMYM2 (zinc finger MYM-type containing 2)
Description:
Involved in the negative regulation of transcription.
Synonyms: FIM; RAMP; ZNF198; MYM; NECRC; SCLL
Tractability: PROTAC: UniProt records ubiquitination sites on it; ubiquitination databases record sites on it; its protein half-life has been measured.
Gene: Protein-coding gene on chromosome 13 (19,958,677 to 20,091,829, forward strand). Ensembl gene ENSG00000121741.
Subcellular location: Nucleus
Subcellular location (Human Protein Atlas): Nucleoplasm; Cytosol; Endoplasmic reticulum
Pathways (Reactome):
Disease: Signaling by FGFR1 in disease; Signaling by FLT3 fusion proteins; Signaling by cytosolic FGFR1 fusion mutants
Cell-Cell communication: Negative Regulation of CDH1 Gene Transcription
Gene Ontology:
Molecular function: protein binding; ubiquitin conjugating enzyme binding; zinc ion binding
Biological process: negative regulation of DNA-templated transcription
Cellular component: nucleoplasm; nucleus; PML body; cytosol
Genetic constraint (gnomAD): Loss-of-function variants: 52 observed, 135.81 expected, observed/expected ratio (o/e) 0.38, 90% interval 0.31 to 0.48. The upper end of that interval is the gene's LOEUF score, 0.48, which puts it in group 2 of 6, group 1 being the genes least tolerant of losing a copy. Missense variants: 1,235 observed, 1,544.3 expected, observed/expected ratio (o/e) 0.8, 90% interval 0.76 to 0.84. Synonymous variants: 488 observed, 520.22 expected, observed/expected ratio (o/e) 0.94, 90% interval 0.87 to 1.01.
Gene-disease validity (ClinGen):
ClinGen rates the evidence that ZMYM2 causes each of these diseases.
syndromic complex neurodevelopmental disorder (autosomal dominant): Definitive. A disorder that involves more than one phenotype associated with the central nervous system, including but not limited to intellectual disability, autism, and seizures (epilepsy), and also a distinctive pattern of other features including dysmorphisms and/or congenital malformations.
Homologues: Orthologues: chimpanzee ZMYM2 (99% identical), macaque ZMYM2 (99% identical), dog ZMYM2 (98% identical), mouse Zmym2 (96% identical), rat Zmym2 (96% identical), rabbit ZMYM2 (95% identical), guinea pig ZMYM2 (91% identical), pig ZMYM2 (90% identical), tropical clawed frog zmym2 (68% identical), zebrafish zmym2 (52% identical). Paralogues in human: ZMYM3 (39% identical), ZMYM4 (36% identical), ZMYM5 (27% identical), ZMYM6 (22% identical), ZMYM1 (16% identical), QRICH1 (14% identical), GTF2IRD1 (7% identical), KIAA1958 (7% identical), THAP12 (6% identical), SCAND3 (5% identical), ZBED5 (5% identical), ZBED11 (5% identical), and 6 more.
Diseases named in the same sentence as ZMYM2 in open-access papers:
ZMYM2 is named in the same sentence as 48 diseases in open-access papers, as found by Europe PMC text mining. Sharing a sentence is not in itself a finding about the gene and the disease. The quoted sentences say what the papers report.
myeloproliferative disease (5 papers, 2011 to 2023). "The zinc finger protein ZMYM2 (otherwise known as ZNF198) was originally identified as part of an oncogenic fusion protein with the receptor tyrosine kinase FGFR1 in myeloproliferative disease." (PMID 37934570, 2023). "ZMYM2 (also known as ZnF198) is fused with the FGFR1 receptor tyrosine kinase in bone marrow cells from patients with an atypical myeloproliferative disease and its expression as a fusion with FGFR1 renders cells sensitive to UV irradiation." (PMID 35253893, 2022). "A chromosomal translocation between ZMYM2 and fibroblast growth factor receptor 1 (FGFR1) causes lymphoblastic lymphoma and a myeloproliferative disorder." (PMID 22011512, 2011). "ZMYM2 has initially attacted attention because it is involved in chromosomal translocations generating ZMYM2/FGFR1 fusion proteins that lead to constitutive FGFR1 signaling and the development of a myeloproliferative disease eventually progressing to AML42,43." (PMID 32439918, 2020). "ZMYM2, which is FGFR1 (fibroblast growth factor receptor 1) is one of the most common chaperones, and patients with ZMYM2-FGFR1 fusions frequently present with myeloproliferative neoplasms and T-lymphocytic lymphomas." (PMID 36712973, 2022).
Intellectual disability (4 papers, 2008 to 2025). "In CAKUT patients carrying heterozygous nonsense or frameshift mutations in ZMYM2, various neurological manifestations have been observed, including microcephaly, developmental delay, intellectual disability, speech delay, and infantile hypotonia." (PMID 41306918, 2025). "The other genes are potassium channel tetramerization domain containing 1 (KCTD1), zinc finger, myeloproliferative and mental retardation type 2 (ZMYM2)/zinc finger protein 198 (ZNF198), ZMYM3/ZNF261, ZMYM4/ZNF262 and glutamine-rich protein 1 (QRICH1)." (PMID 22011512, 2011). "Notably, microcephaly in patients with ZMYM2 mutations is not fully penetrant, and the severity of intellectual disability varies among individuals, suggesting that other environmental or genetic factors may influence disease." (PMID 40313719, 2025).
leukemia (4 papers, 2013 to 2025). A malignant (clonal) hematologic disorder, involving hematopoietic stem cells and characterized by the presence of primitive or atypical myeloid or lymphoid cells in the bone marrow and the blood. "In this report we describe the case of a patient with a ZMYM2:FGFR1 fusion-driven leukemia who was successfully treated with FGFR kinase-targeting inhibitors." (PMID 40881645, 2025).
ovarian carcinoma (3 papers, 2023 to 2026). A malignant neoplasm originating from the surface ovarian epithelium. "Collectively, these findings identify a glycolysis-lactate-ZMYM2 lactylation axis that promotes platinum resistance in ovarian cancer and highlight lactylation-dependent ZMYM2 stabilization as a potential therapeutic vulnerability." (PMID 42278240, 2026). "The overexpression of ZMYM2 was also detected in human ovarian cancer, which could remarkedly promote tumor growth in vitro and in vivo." (PMID 37031178, 2023). "Additionally, the ubiquitin-binding enzyme E2B (UBE2B) can facilitate the monoubiquitination of the transcription regulator zinc finger MYM-type protein 2 (ZMYM2) mediated by the ubiquitin E3 ligase ring finger protein 73 (RNF73), thereby promoting the growth of ovarian cancer." (PMID 39048965, 2024).
schizophrenia (3 papers, 2021 to 2025). A major psychotic disorder characterized by abnormalities in the perception or expression of reality. "We meta-analyzed large-scale brain transcriptomic data from mice harboring individual loss-of-function mutations in seven schizophrenia risk genes (Akap11, Dagla, Gria3, Grin2a, Sp4, Srrm2, Zmym2)." (PMID 41022686, 2025). "Further studies examining the function of the encoded protein during neurodevelopment, and analysis of larger psychiatric cohorts, are required to establish a robust link between LoF variants in ZMYM2 and schizophrenia pathogenesis." (PMID 33526774, 2021). "Comparable to other schizophrenia-associated genes, variants in ZMYM2 appear to manifest pleiotropic effects." (PMID 33526774, 2021). "Genome analyses also identified variants with potential clinical implications, including TREs (one in DMPK; two in ATXN8OS) and ultra-rare loss-of-function SNVs in ZMYM2 (a novel candidate gene for schizophrenia)." (PMID 33526774, 2021). "Additional proteins with schizophrenia rare variant associations (via the SCHEMA consortium) altered in 22q11.2del neurons included DNM3, MAGI2 and TRIO (downregulated in patient neurons) and HIST1H1E, SRRM2 and ZMYM2 (upregulated in patient neurons)." (PMID 35760976, 2022).
Hyperglycemia (2 papers, 2025). An increased concentration of glucose in the blood. "Similar to clinical observations in MODY patients, Zmym2 heterozygous mutant mice exhibited chronic but mild hyperglycemia, with blood glucose levels progressively increasing until 90 days of age." (PMID 40313719, 2025). "Significantly, the ZMYM2 heterozygous mutant mouse model also exhibits metabolic abnormalities, including chronic mild hyperglycemia (progressively elevated blood glucose levels until 90 days of age), significantly reduced fasting serum insulin, and impaired insulin secretion capacity." (PMID 41306918, 2025). "Notably, this study offers new insights into the roles of Zmym2 in embryonic development and identifies a potential link between Zmym2 mutation and MODY, as well as a possible relationship between hyperglycemia and lifespan." (PMID 40313719, 2025).
Infertility (2 papers, 2023 to 2025). "The cranial, cardiac, musculoskeletal, CAKUT and possible infertility phenotype caused by ZMYM2 heterozygosity in humans suggests extensive further roles in development." (PMID 37395395, 2023). "ZMYM2 mutations have been linked to abnormal development of the male reproductive system, and the de novo or mosaic occurrence of these mutations strongly suggest that heterozygous truncating mutations in ZMYM2 convey infertility or interfere with germline transmission." (PMID 40313719, 2025).
lymphoid neoplasm (2 papers, 2021 to 2022). A neoplasm composed of a lymphocytic cell population which is usually malignant (clonal) by molecular genetic and/or immunophenotypic analysis. "ZMYM2 has also been implicated in cancer as a fusion protein with the Fibroblast growth factor receptor 1 (FGFR1) in 8p11 myeloproliferative syndrome (EMS), where it constitutes ∼ 50% of all cases of FGFR1-fusion related myeloid/lymphoid neoplasms." (PMID 35253893, 2022).
acute lymphoblastic leukemia (1 paper, 2021). Leukemia with an acute onset, characterized by the presence of lymphoblasts in the bone marrow and the peripheral blood. "Unlike other IMiDs or CELMoDs, avadomide degrades ZNF198 (or ZMYM2) fusion oncoproteins, such as ZNYM2-FGFR1 and ZMYM2-FLT3, indicating potential benefit for patients with acute lymphoblastic leukemias harboring these translocations." (PMID 34834536, 2021).
acute myeloid leukaemia (1 paper, 2022). "ZMYM2 was first characterised as a protein responsible for the induction of 8p11 myeloproliferative syndrome (EMS)/stem cell leukaemia-lymphoma (SCLL) by chromosomal translocation to FGFR146,47, resulting in rapid transformation to acute myeloid leukaemia (AML) and T-lymphoblastic lymphoma." (PMID 35013300, 2022).
Anxiety (1 paper, 2025). Intense feelings of nervousness, tension, or panic often arise in response to interpersonal stresses. "Male Zmym2 PB/+ mice were significantly more active than male Zmym2 +/+ controls during the first 15 min of the test and spent less time in the center of the chamber suggesting increased anxiety-like behavior." (PMID 40313719, 2025). "This study provides the first comprehensive characterization of phenotypes in Zmym2 mutant mice with the PB insertion, including embryonic lethality, genitourinary defects, anxiety and aggressive-like behavior, and glucose metabolism disorders." (PMID 40313719, 2025). "Even in the absence of obvious craniofacial abnormalities, Zmym2 PB/+ mice exhibited behavioral abnormalities, including anxiety and aggressive-like behaviors, uncovering a previously unrecognized neurologic phenotype." (PMID 40313719, 2025).
chronic myelomonocytic leukemia (1 paper, 2024). A myelodysplastic/myeloproliferative neoplasm which is characterized by persistent monocytosis, absence of a Philadelphia chromosome and BCR/ABL fusion gene, fewer than 20 percent blasts in the bone marrow and blood, myelodysplasia, and absence of PDGFRA or PDGFRB rearrangement. "For example, ZMYM2::FGFR1 most commonly presents as a T-lymphoblastic leukemia/lymphoma, BCR::FGFR1 and TPR::FGFR1 present histologically similar to chronic myeloid leukemia (CML), and CEP43::FGFR1 and CNTRL::FGFR1 show features similar to chronic myelomonocytic leukemia (CMML)." (PMID 38611061, 2024).
colorectal tumor (1 paper, 2025). "Our findings reveal that ZMYM2 expression is significantly elevated in colorectal tumor tissues compared to adjacent normal tissues." (PMID 40427072, 2025).
cryptorchidism (1 paper, 2025). The failure of one or both testes of a male fetus to descend from the abdomen into the scrotum during the late part of pregnancy. "Additionally, some Zmym2 PB/+ mice displayed unilateral cryptorchidism (22.22%, 2/9), bilateral cryptorchidism with hydrocele (11.11%, 1/9) or intratesticular cysts (11.11%, 1/9)." (PMID 40313719, 2025).
cystic kidneys (1 paper, 2025). "Zmym2 +/− mice exhibited a spectrum of CAKUT-like defects, including hydroureter, duplex and cystic kidneys, and VUR." (PMID 40313719, 2025).
male infertility (1 paper, 2025). The inability of the male to effect fertilization of an ovum after a specified period of unprotected intercourse. "Although Zmym2 mutations alone did not induce male infertility in mice, they led to structural abnormalities in the reproductive system and impaired sperm motility, suggesting that ZMYM2 may be one of the genes involved in male infertility." (PMID 40313719, 2025).
maturity-onset diabetes (1 paper, 2025). "Notably, the most significantly downregulated DEGs associated with Zmym2 mutation were linked to maturity-onset diabetes of the young (MODY)." (PMID 40313719, 2025).
MODY (1 paper, 2025). "RNA-Seq data provided unexpected findings, revealing a direct mechanistic link between Zmym2 mutation and MODY." (PMID 40313719, 2025).
non-small cell lung carcinoma (1 paper, 2022). A group of at least three distinct histological types of lung cancer, including non-small cell squamous cell carcinoma, adenocarcinoma, and large cell carcinoma. "ZMYM2 mutations have also been observed in other cancers including uterine corpus endometrial carcinoma (UCEC) and non-small cell lung cancer (NSCLC), including as a cancer driver gene in UCEC." (PMID 35253893, 2022).
posterior fossa ependymoma (1 paper, 2022). A high grade ependymoma that is located within the posterior fossa. "Interestingly, 6/7 of the constrained genes in which pLoF variants were found in patients with posterior fossa ependymoma show particularly high expression levels in cerebellar tissue (UHRF2, FOXO3, CDC42BPA, ZMYM2, CHD6 and DNAJC2)." (PMID 36008825, 2022).
scoliosis (1 paper, 2025). A congenital or acquired spinal deformity characterized by lateral curvature of the spine. "Patients carrying ZMYM2 mutations also exhibit extra-renal abnormalities, including cardiac septal defects, skeletal abnormalities, hypoplastic hands, feet and nails, as well as scoliosis." (PMID 40313719, 2025).
cancer (9 papers, 2017 to 2023). A tumor composed of atypical neoplastic, often pleomorphic cells that invade other tissues. "As highlighted by Mas-Ponte and Supek, APOBEC/AID driven mutations tend to be directed towards early-replicating, gene-rich regions of the genome, inducing deleterious events on several genes including ZMYM2, which our pan-cancer model has linked with G0 arrest." (PMID 37221612, 2023). "The ZMYM2 protein was a zinc finger protein which participate into a histone deacetylase complex which was activated in many kinds of cancers to inhibit the functions of tumor suppressor genes." (PMID 37031178, 2023). "As mutations in ZMYM2 and ZMYM3 have been identified in several cancers, these results may reveal cancer-relevant functions of these poorly characterized ZnF proteins." (PMID 35253893, 2022). "Taken together, our results showed that pomalidomide could be a candidate drug for treating cancers driven by ZMYM2 and FGFR1 fusion, such as EMS." (PMID 35013300, 2022). "Indeed, both ZMYM2 and ZMYM3 have been implicated in several human diseases including cancer." (PMID 35253893, 2022). "Considering our identification of ZMYM2 as a DDR factor involved in maintaining genome integrity, we speculate that ZMYM2 mutations may result in genome instability, a known contributing factor involved in cancer." (PMID 35253893, 2022). "To further explore the functional importance and involvement of ZMYM2 in DSB repair, we investigated the cellular consequences of depleting ZMYM2 in human cancer cells." (PMID 35253893, 2022). "Transcription factor targets included NR1H4, ZMYM2 and ZNF436, which might be metabolism-related and cancer-related factors." (PMID 35410157, 2022).
tumor (5 papers, 2015 to 2025). "Silencing ZMYM2 suppressed tumor cell growth and restored chemosensitivity." (PMID 40427072, 2025). "Some neoplastic events enriched in tumours with increased G0 arrest, such as p16 or ZMYM2 deletions, could mark elevated genomic stress that renders cells more prone to cell cycle exit." (PMID 37221612, 2023). "However, our analysis has also uncovered novel dependencies of G0 arrest-proliferation decisions that have not been reported previously, such as CEP89 and LMNA amplifications observed in fast cycling tumours, or ZMYM2 deletions prevalent in samples with high levels of G0 arrest." (PMID 37221612, 2023).
infection (2 papers, 2012 to 2017). The state of being infected such as from the introduction of a foreign agent such as serum, vaccine, antigenic substance or organism. "Various repressors of apoptosis such as Ilf3, Zmym2, Satb1, Ccl21 and Scd were downregulated and expression levels of inducers of apoptosis such as Daxx, Oas1, Lcn2 and Gng2 were upregulated with V3000 infection at 24 h pi resulting in an overall activation of the apoptotic pathway." (PMID 28446152, 2017).
genetic disorders (1 paper, 2025). "Additionally, men with ZMYM2 mutation may be more susceptible to pathological factors and lifestyle influences, including other genetic disorders, genital tract infections, environmental pollutants, and smoking." (PMID 40313719, 2025).
hematopoietic neoplasm (1 paper, 2021). "To date, more than 14 FGFR1 fusion partners in hematopoietic neoplasm have been described, and the zinc-finger domain ZNF198 (also known as ZMYM2) on chromosome 13q12 is the most typical partner gene." (PMID 34732230, 2021).
ZMYM2 also shares sentences with these, for which no sentence is quoted: acute leukemia (2 papers); developmental delay (2); hepatic carcinoma (2); microcephaly (2); alveolar rhabdomyosarcoma (1); chronic myeloid leukaemia (1); eosinophilia (1); gastric cancer (1); glucose metabolism disorders (1); Hodgkins lymphoma (1); hydrocele (1); Hydroureter (1); intestinal T-cell lymphoma (1); lymphoblastic lymphoma (1); lymphoma (1); myeloproliferative neoplasm (1); non-Hodgkin lymphoma (1); parasitic infections (1); pertussis (1); speech delay (1); T-cell lymphoma (1); uterine corpus endometrial carcinoma (1).